IL2 (interleukin 2)
Diseases named in the same sentence as IL2 in open-access papers (continued):
Sharing a sentence is not in itself a finding about the gene and the disease.
Autoimmunity (continued). "Cohort survival was consistent with a cohort treated with low-dose IL-2, a CD4 Treg-directed immune therapy used clinically to treat patients with steroid-refractory GvHD or autoimmunity." (PMID 39559361, 2024). "Collectively, these results reveal that a strong sustained IL-2 signal, even if selective for IL-2Rα+ cells, potentiates antigen-induced CD8+ T-cell antitumor immunity and autoimmunity despite its concomitant stimulatory effects on Tregs." (PMID 36705564, 2023). "Th1 cells and related transcription factor T-bet and inflammatory cytokines including IFNγ, TNFα, IL-2, IL-18, TGF-β, and IL-12 are important in inflammatory responses such as autoimmunity development." (PMID 38164134, 2023). "The Th1 cell family including Th1 cells, transcription factor T-bet, and related cytokines IFNγ, TNFα, IL-2, IL-18, TGF-β, and IL-12 have been widely discussed in autoimmunity, such as SLE." (PMID 38164134, 2023). "miR-181c has been shown to enhance Th17 differentiation and promote autoimmunity through targeting Smad7 and modulating TGF-β pathway and IL-2 expression." (PMID 34804042, 2021). "Administration of low-dose interleukin 2 (IL2) preferentially expands Tregs, and is being studied as a treatment choice in several autoimmune conditions." (PMID 32111171, 2020). "In vivo, both low-dose IL-2 therapy and TNF receptor 2 (TNFR2) agonism were shown to expand Tregs and alleviate autoimmunity." (PMID 31920671, 2019). "On the other hand, opposing results showed that IL-2 administration reversed type I diabetes in NOD mice; IL-2 induced oral tolerance in a murine model of autoimmunity and in vivo suppression by Tregs." (PMID 26529512, 2015). "IL-2−/−, IL-2Rα−/−, or IL-2Rβ−/− KO mice have decreased numbers of natural CD4+CD25+ Tregs and suffer from autoimmunity or fatal lymphoproliferative disease." (PMID 22984435, 2012). "In this trial, only one patient developed an autoimmune disorder, vitiligo, as a result of DAB/IL2 administration." (PMID 22165955, 2011). "CD25 is the alpha chain of the trimeric receptor of IL-2, and lack of CD25 not only causes autoimmunity due to immunosuppression but also increases the risk of many infections as IL-2 has pivotal roles in inducing Th1 and CD8 + cytotoxic T cells." (PMID 40587482, 2025). "IL‐2 muteins without complexing with anti‐IL‐2 can induce preferential expansion of Tregs and control autoimmunity." (PMID 38504554, 2024). "Interleukin 2 is secreted by activated T lymphocytes (both CD4+ and CD8+) and plays an important role in the proliferation of T and B lymphocytes by inducing effector T lymphocytes as well as generating Tregs that can prevent autoimmunity." (PMID 39015324, 2024). "The consequence of the dependency of Treg on IL-2 is the development of autoimmunity in the absence of IL-2 signalling." (PMID 37741949, 2023). "Mice lacking IL2 die from lethal T-cell–driven autoimmunity due to reduced functional Tregs, indicating that IL2 signaling is essential for excessive T-cell activation." (PMID 35833132, 2022). "We show that provision of IL-2 can compensate for costimulation blockade in Treg, but not Tconv, and that combining these interventions elicits robust regulation of autoimmunity in a mouse model of diabetes." (PMID 36347877, 2022). "More than that, in IL-2 wild type (Il2+/+) and Il2-/- bone marrow chimera mice, tTreg cell generation was totally rectified in Il2-/- thymocytes and these bone marrow chimera mice did not develop autoimmunity." (PMID 35432378, 2022). "The discovery that mice lacking IL-2 exhibit uncontrolled T cell activation and rampant autoimmunity explained just how crucial IL-2 is for the development, homeostasis and suppressive function of Tregs." (PMID 32977677, 2020). "The absence of autoimmunity in this setting implies that the increase in eTregs is a direct physiological consequence of IL-2 deprivation." (PMID 30833563, 2019).
Autoimmunity (continued). "For this, we first generated bone marrow (BM) chimera reconstituted with a 50:50 ratio of WT and IL-2−/− BM cells to avoid spontaneous T cell activation due to autoimmunity in IL-2−/− mice and 8 weeks later, naïve CD4+ T cells derived from WT and IL-2−/− BM were isolated from the chimeric mice." (PMID 30190718, 2018). "Our study uncovered that the IL-2 signaling under steady state is critical for direct inhibition of Th17 differentiation, without the participation of Treg cells, in preventing autoimmunity." (PMID 30150979, 2018). "Lack of IL-2 or its receptor chains leads to fatal autoimmunity because Treg cells are unstable and fail to suppress autoreactive Tconv cells." (PMID 30560927, 2018). "Since pathogenic mechanisms are already well established at the time of JES6/IL-2 therapy (4 weeks after cGvHD induction), Treg expansion was not able to ameliorate the ongoing autoimmunity." (PMID 29670626, 2018). "The lack of IL-2, its high affinity receptor chain IL-2Rα/CD25 or its transducing chain IL-2Rβ/CD12220, lead to the development of wasting autoimmunity as a result of the loss of stable Foxp3 expression and subsequent Foxp3+ Treg cells in the periphery." (PMID 30560927, 2018). "In addition, we reported that IL-2-induced STAT5 activation limits Th17 differentiation and related autoimmunity in a murine model via competing the IL-6-induced STAT3 binding to the Il17a/f locus, in a FOXP3-independent fashion." (PMID 30150979, 2018). "Moreover, DCs employ the IL-2-mediated STAT5 signalling axis to promote the death of PAMP-stimulated GM-DCs to maintain immune tolerance and prevent autoimmunity." (PMID 27293315, 2016). "Additionally, IL-2 complexes containing the anti-IL-2 mAb clone JES6-1A12 have been studied for their beneficial role in Treg expansion and activation in models of autoimmunity, infection and cancer." (PMID 27391012, 2016). "Subsequently, Treg cell expansion induced by the administration of the IL-2 complex has therapeutic applications in graft injection and autoimmune and inflammatory diseases without inducing toxicity." (PMID 27144181, 2016). "SCID mice have defective peripheral T and B cells, and IL-2 gene deletion in the peripheral immune system of SCID background mice does not result in the development autoimmunity (as it does in WT mice)." (PMID 25961067, 2015). "In addition to IL-2, other factors are also known to support Treg maintenance in vivo and Treg are present in IL-2−/− as well as CD25−/− mice, though both strains do develop autoimmunity." (PMID 26448755, 2015). "Lack of IL-2 leads to virus-induced overt lymphoproliferative disease and autoimmunity, which, depending on the genetic background, manifests itself primarily as inflammatory bowel disease or hemolytic anemia." (PMID 25946103, 2015). "As interleukin-2 paradoxically affects both tolerance and immunity in the absence of T-regulatory cells, HD-IL-2 increases effector CD8+ cytotoxic function which is responsible for both autoimmunity and tumor regression." (PMID 25245327, 2014). "Actually, in the mouse model of autoimmunity, it has been observed that an absence of IL-2 resulted in insufficient Treg expansion, while it disturbed neither Teff expansion nor Teff responses to enhanced levels of the pro-inflammatory cytokine IL-15." (PMID 25322151, 2014). "We aimed to investigate for the first time the potential influence of the IL2/IL21, IL2RA and IL2RB most associated polymorphisms with autoimmunity on the endogenous non-anterior uveitis genetic predisposition." (PMID 23676143, 2013). "In contrast to Teff, regulatory T cells (Treg) which are essential for suppressing autoimmunity do not produce IL-2 themselves, but paradoxically are highly dependent on IL-2 for their survival and function." (PMID 24376757, 2013).
Autoimmunity (continued). "Furthermore, administration of a relatively “lower” dose of IL-2 (complexed with anti-IL-2) promotes survival of Tregs within islets and retards the development of diabetes in NOD mice and prevents autoimmunity in IL-2−/−/Bim−/− double KO mice." (PMID 22984435, 2012). "Fluctuations in the bio-availability of IL-2 in inflammatory sites may perturb the TREG/TEFF balance in these sites and trigger autoimmunity." (PMID 22545118, 2012). "The absence of IL-2 results in the development of lethal autoimmunity and abnormal high level of IL-2 impairs the functions of many immune cells." (PMID 23185455, 2012). "Indeed, IL-2 signals seem to be pivotal for Treg survival because animals that lack IL-2, CD25, or CD122 are largely devoid of peripheral Treg and suffer from severe autoimmunity." (PMID 22807926, 2012). "No clinical manifestations of acute toxicity, autoimmunity or cardiotoxicity were observed after administration of Her2-pDNA in combination with GM-CSF, IL-2 and trastuzumab." (PMID 20529245, 2010). "In addition to TCR signals, IL2 plays a key role, as indicated by defective thymic Treg development and subsequent autoimmunity in mice lacking IL2, or its high-affinity receptor chain CD25 (also called IL2Rα)." (PMID 38980291, 2024). "In the current study, IL-2 and IL-15 stimulation was identified to preferentially shift NK cell from NK0 (inactivated status) to a dominant NK1 phenotype, which could potentially lead to long-term inflammation and development of autoimmunity in the culture." (PMID 38106519, 2023). "Evidence that InsB-g7 CAR Tregs potently suppress IL-2 production suggests that consumption of IL-2 could contribute to a negative feedback loop to prevent autoimmunity." (PMID 37561596, 2023). "IL-2 is arguably the most important growth factor for T regulatory cell function and increases the expression of FOXP3 and Treg suppression molecules with the ability to inhibit the activation of perforin or granzymes released from killer CD8+ T cells, limiting autoimmunity." (PMID 36359899, 2022). "IL-2 is also critical for the development of Tregs in the thymus and for their maintenance and function in the periphery; index patient’s normal numbers of Tregs and the lacking severe autoimmunity further confirmed hypomorphism." (PMID 32072341, 2020). "This concerted dual T- and B-cell adaptive autoimmune response strongly supports the hypothesis that tolerance to IL-2 is broken in T1D, demonstrating uniquely that autoimmunity is also directed against non-islet antigens in T1D." (PMID 27708334, 2016). "Moreover, these cells did not secrete either IFNγ or IL-2 cytokines following T cell stimulation, suggesting their ability to suppress autoimmunity." (PMID 23243423, 2012). "Interestingly, the adoptive transfer of WT Treg cells either in IL-2-/- or IL-2R-/- mice can only prevent autoimmunity in IL-2R-/-, and not IL-2-/-, mice." (PMID 21059266, 2010). "Thus, IL-2 in the form of an immune complex can efficiently substitute for CD4 help, promoting the differentiation of CTL capable of overcoming self-tolerance and inducing autoimmunity under lymphopenic conditions." (PMID 20856822, 2010). "As well, the function of T-Regs in the periphery is also totally dependent on IL2/IL2R signaling, so that if potential positively selected autoreactive T cells are not continuously suppressed by T-Regs, the IL2 (-/-) syndrome of lymphoid hyperplasia and autoimmunity will occur." (PMID 15606917, 2004). "IL-2 signaling also regulates immune tolerance, with Il2−/−, Il2ra−/−, and Il2rb−/− mice developing autoimmunity, while adoptive transfer of Treg cells into Il2rb−/− mice prevents autoimmunity, consistent with the nonredundant role of IL-2 in the development of Treg cells." (PMID 40680114, 2025).
Autoimmunity (continued). "Because IL-2 regulates the differentiation of the TH1, TH2, and TH17 CD4+ T helper cell subsets, we hypothesized that part of the mechanism by which IL-2 counteracts autoimmunity could be via an alteration in the balance of these cell types and the cytokines that they produce." (PMID 27095999, 2015). "The administration of agonistic IL-2 immunocomplexes phenocopies the absence of Tregs, i.e., it induces KILR CD8+ T cells, promotes autoimmunity, and enhances antitumor responses in mice." (PMID 36705564, 2023). "Mice lacking this subunit in T cells have less autoimmunity and PPP2R2D negatively regulates IL-2 production in conventional T cells by regulating the chromatin opening of the IL-2 gene." (PMID 33597953, 2020). "Non-HLA findings include modifications in genes related to autoimmunity (IL2/IL2RA), bile acid toxicity (GPBAR1), and mechanisms related to concomitant IBD (IL2/IL21, ILR2A, CARD9, MST1, Fut2, and SIK2)." (PMID 27882046, 2016). "This is likely compounded by the lack of IL-2 production from WAS effector T cells, although in vivo the presence of wildtype effector T cells with normal IL-2 secretion is unable to prevent autoimmunity." (PMID 24117828, 2013). "Since the point of control over immune reactivity occurs at IL2 gene expression, it is logical that defects in the IL2/FOXP3 negative feedback loop may lead to a preponderance of activating signals and autoimmunity." (PMID 18324310, 2008).
renal cell carcinoma (259 papers, 1990 to 2025). "Based on preclinical data suggesting a synergism between IL-2 and 5-fluorouracil (5-FU) on one hand and IFNα and 5-FU on the other, added to the well-known synergism of the association of IL-2 and IFNα, the combination of IL-2, IFNα and 5-FU has been investigated in renal cell carcinoma." (PMID 14676797, 2003). "At present, the only wild-type (WT) recombinant IL2 cancer treatment approved for usage is aldesleukin, which is available for metastatic melanoma or renal cell carcinoma (RCC) in several countries worldwide." (PMID 39140264, 2024). "A trial with stage I-II renal cell carcinoma patients revealed that IL-2 administered in the early morning (5:00–13:00) or late night (21:00–5:00) resulted in longer survival compared to afternoon administration (13:00–21:00)." (PMID 39744625, 2024). "For example, T-cell lymphoma, classic Hodgkin lymphoma, SM, AML, MPN, and certain solid tumors (e.g., lung cancer, renal cell carcinoma, etc.)can abnormally release IL-2, IL-3, IL-5 or GM-CSF." (PMID 38611061, 2024). "Immunotherapy drugs used in the treatment of renal cell carcinoma in China include nivolumab, pembrolizumab, interleukin 2 and recombinant human interferon α2b.For medium to high-risk patients, dual immunotherapy is superior to single targeted therapy." (PMID 39023752, 2024). "To date, two cytokines have received FDA approval: IL-2 for renal cell carcinoma (RCC) and metastatic melanoma and IFNα for hairy-cell leukemia follicular non-Hodgkin lymphoma and melanoma." (PMID 38785789, 2024). "In 1992, the US Food and Drug Administration (US-FDA) approved high-dose (HD) IL-2 (aldesleukin) for the treatment of renal cell carcinoma (RCC)." (PMID 39114660, 2024). "First attempts were performed for advanced renal cell carcinoma and metastatic melanoma: recombinant human interleukin-2 (rhIL-2) used in these settings, was capable of favoring human T cell growth." (PMID 37509328, 2023). "The first experiences were reported in the 1980s, and concerned the development of IL-2 for the treatment of melanoma and renal cell carcinoma." (PMID 37509328, 2023). "Recombinant IL2 (Proleukin®), which is approved for the treatment of renal cell carcinoma and metastatic melanoma, induced durable complete responses in a small proportion of cancer patients." (PMID 36839699, 2023). "Proleukin (recombinant human interleukin-2) has been identified as an effective therapy for metastatic melanoma and renal cell carcinoma (RCC)." (PMID 37828948, 2023). "The recombinant human cytokine interleukin-2 (rhIL-2, or aldesleukin) was originally approved as a drug for immune oncology targeting renal cell carcinoma." (PMID 35685243, 2022). "For example, a positive thyroid autoantibody titer was highly correlated with increased survival in patients with renal cell carcinoma who received interleukin-2 (IL-2) and interferon-alfa 2 therapy." (PMID 34205851, 2021). "For these reasons, the therapeutic use of IL2 is currently limited to patients with advanced renal cell carcinoma and melanoma." (PMID 33579033, 2021). "The incidence of renal cell carcinoma is growing year by year, and for patients with advanced renal cell carcinoma, IL-2 is the first option." (PMID 33767709, 2021). "Based on current data, the United States Food and Drug Administration (FDA) approval has been granted for the use of HD IL2 therapy for the treatment of renal cell carcinoma and metastatic melanoma." (PMID 33579033, 2021). "The efficacy of B7-1 (CD-86) transduced autologous tumor cell vaccine combined with IL-2 was evaluated in a single center phase II trial for the treatment of stage IV renal cell carcinoma." (PMID 33767709, 2021). "While we have come a long way from the use of IL-2 to immune checkpoint inhibitors in the treatment of renal cell carcinomas, this is still just the beginning of the immunotherapeutics era in RCC." (PMID 34452045, 2021).